LINC00850 (long independently transcribed non-coding RNA 850)
Synonyms: KUCG1
Gene: Long non-coding RNA gene on chromosome X (149,825,708 to 149,879,799, forward strand). Ensembl gene ENSG00000280752.
Diseases named in the same sentence as LINC00850 in open-access papers:
LINC00850 is named in the same sentence as 2 diseases in open-access papers, as found by Europe PMC text mining. Sharing a sentence is not in itself a finding about the gene and the disease.
LINC00850 shares sentences with these, for which no sentence is quoted: breast carcinoma (1 paper); lung carcinoma (1).